SSTR2 (somatostatin receptor 2)
Diseases named in the same sentence as SSTR2 in open-access papers (continued):
Sharing a sentence is not in itself a finding about the gene and the disease.
meningioma (continued). "Binding properties of 800CW-TATE to SSTR2 were tested ex vivo on ten frozen meningioma samples." (PMID 34633509, 2021). "It targets somatostatin receptor subtype 2 (SSTR2), which is overexpressed in all meningiomas." (PMID 33768405, 2021). "The purpose of this investigation was to evaluate if a relationship exists between tumor vascularity and SSTR2 expression, which may play a role in meningioma prognostication and clinical management." (PMID 35155210, 2021). "In the near future, we will further investigate factors relating to meningioma treatment with SSTR2 ADC, such as dosage optimization, survival, pharmacodynamics analysis, toxicology, and biodistribution, to collect translational data to facilitate the possible clinical evaluations." (PMID 34063284, 2021). "SSTR2-targeted tracers have already been applied for diagnostics and treatment of meningiomas." (PMID 33768405, 2021). "The SSTRs showed variable specificity for meningiomas, and SSTR2 appeared to be the most specific." (PMID 34830858, 2021). "Clinical studies demonstrated that SSTR2 is an ideal surface receptor to target meningiomas." (PMID 34063284, 2021). "Moreover, given that SSTR2 is expressed in almost 100% meningiomas, radiolabeled SSTR2 ligands have been widely utilized in the modern radiological diagnosis of meningioma." (PMID 33014821, 2020). "Hence, we provide a detailed summary of the current understanding of the clinical significance of SSTR2 in meningioma in this review." (PMID 33014821, 2020). "SSTR2 is also expressed widely and represents manifold functions in various tumor tissues including neuroendocrine tumors, pituitary adenomas, breast cancer, melanoma, thyroid cancer, and meningioma." (PMID 33014821, 2020). "Furthermore, in the case of atypical meningioma or a rare type of meningioma like optic nerve sheath meningioma, SSTR2-related PET/CT is also deemed to be a useful noninvasive diagnostic method." (PMID 33014821, 2020). "Studies regarding the detection methods and expression of SSTR2 in meningiomas." (PMID 33014821, 2020). "Accumulating studies have revealed the crucial clinical significance of SSTR2 in meningioma." (PMID 33014821, 2020). "For instance, SPECT/CT SRS using 99mTc-HYNIC-octreotide specifically binding to SSTR2 in meningioma can diagnose primary optic nerve sheath meningioma or allow differentiation of meningiomas from inactive pituitary adenomas, which is seemingly elusive by conventional MRI." (PMID 33014821, 2020). "These researches indicate that whether SSTR2 levels are grade related in meningiomas remains controversial; meanwhile, SSTR2 could still offer some implications for prognosis prediction in spite of this controversy." (PMID 33014821, 2020). "Interestingly, the majority of meningiomas express somatostatin receptors, with SSTR2 being the most common detected in 100% of tumors." (PMID 31220093, 2019). "Somatostatin receptor subtype 2 (SSTR2) upregulation is very common in meningiomas." (PMID 31187231, 2019). "Notably, SSTR2 expression on gallium-68-DOTATOC PET imaging was significantly lower in WHO III meningiomas compared to WHO I/II meningiomas." (PMID 31187231, 2019). "According to TASC analysis, SSTR-2 is the most promising receptor for meningioma targeting." (PMID 29858948, 2018). "Although patients with high grade lesions may benefit the most from intraoperative imaging, WHO I meningiomas are still a representable model as SSTR-2 is expressed in all meningiomas, regardless the grade." (PMID 29858948, 2018). "The meningioma component was strongly positive for SSTR2 and PR." (PMID 29698064, 2018). "SSTR2-targeted radionuclide therapy, commonly referred to as ‘peptide receptor radionuclide therapy’ (PRRT) has been acknowledged by the European Association of Neuro-oncology (EANO) as a salvage therapy for treatment-refractory meningioma, as outlined in recent practice guidelines." (PMID 41091274, 2025).
meningioma (continued). "Interestingly, we could not detect a significant increase in 53BP1 foci numbers compared to controls at both day 0 and day 2 post-therapy for one meningioma sample (MO-12), for which tumor tissue stained only weakly for SSTR2." (PMID 39061156, 2024). "In addition, we detected a decrease in SSTR2 expression over time for meningioma spheroids." (PMID 39061156, 2024). "However, only one study has reported SSTR2 expression in canine meningiomas." (PMID 39011594, 2024). "Similar to “TargomiRs”, which showed interesting preliminary results in mesothelioma, this miR could be specifically addressed to meningioma tumor cells through vectors loaded with miR-16 mimics and targeted to receptors specifically expressed by meningioma cells (e.g., SSTR2)." (PMID 37601663, 2023). "However, positron emission tomography (PET) imaging of somatostatin receptor subtype 2 (SSTR2) expression using 68Ga-DOTATATE may provide a higher sensitivity for meningioma detection, especially in cases with complex anatomy or in the recurrent setting." (PMID 36313670, 2022). "With high expression of somatostatin receptor 2 (SSTR2) on meningioma cells, positron emission tomography (PET) imaging using SSTR ligands such as 68Ga-DOTATOC and 68Ga DOTATATE has been used as a diagnostic tool and to help delineate healthy tissue from meningiomas." (PMID 33801089, 2021). "Somatostatin receptor subtype 2 (SSTR2)-based positron emission tomography (PET), in particular 68Ga-DOTATOC, 68Ga-DOTATATE, and 68Ga-DOTANOC, has been reported as a useful diagnostic tool in meningioma patients, with level 2 evidence in tumor contouring for radiotherapy planning." (PMID 33804251, 2021). "Moreover, our binding and immunohistochemical studies showed that the CH-157MN meningioma cells expressed SSTR2 and, consequently, suggest that both radiotracers could be equally used for imaging and staging patients with meningioma." (PMID 25369268, 2014). "As meningiomas across all WHO grades express high levels of somatostatin receptor 2 (SSTR2), DOTATATE PET/CT and PET/MRI have emerged as a valuable adjunct modality in meningioma staging and management." (PMID 41323179, 2026). "Due to the possibility of meningioma metastasis, 68Ga-DOTATOC PET/MRI of the liver and brain, along with a total body PET/CT, revealed hyper-expression of somatostatin receptor 2 in multiple liver and bone lesions." (PMID 40283171, 2025). "Case 2 describes a 45-year-old man with a de novo anaplastic meningioma (WHO grade 3) who later developed multiple bilateral pulmonary nodules confirmed via robotic-assisted bronchoscopy (EMA+, SSTR2+, CAM5.2-)." (PMID 41552249, 2025). "Other SSTR-2-based PET modalities, such as [68Ga]Ga-DOTATATE and DOTANOC have higher uptake in meningiomas than other metastases due to SSTR-2 receptor expression in these lesions." (PMID 40710005, 2025). "IHC staining revealed strong SSTR2 positivity in the MEN-Os, confirming their resemblance to human meningioma tumors (left-panel)." (PMID 39941893, 2025). "Theranostic SSTR2-targeting via [68Ga]DOTATATE for PET imaging and β-emitting [177Lu]DOTATATE for the treatment of meningiomas are currently under active investigation." (PMID 40149634, 2025). "Meningioma have been shown to frequently overexpress somatostatin receptor type 2 (SSTR2) which makes them targetable for SSTR-directed PET/CT and it has been shown to be useful in diagnostics of meningioma." (PMID 40983935, 2025). "Somatostatin receptor 2 (SSTR2), a highly sensitive and specific meningioma biomarker, can be imaged with [68Ga]-DOTATATE PET, improving diagnosis and treatment." (PMID 41497451, 2025). "Preliminary evidence demonstrates efficacy against meningiomas, which varies by grade with PFS-6 rates of 94%, 48%, and 0% in Grade 1, 2, and 3 SSTR2-positive meningiomas, respectively." (PMID 40149634, 2025).
meningioma (continued). "Expression rate in canine and feline meningioma was slightly higher than the detection rate in human studies, ranging between 62%–98% and 81%–100% for SSTR1 and SSTR2, respectively." (PMID 39011594, 2024). "In feline meningiomas (n = 12), RNA expression of SSTR1, SSTR4, SSTR5 and SSTR2 was detected in 91%, 46%, 46% and 36% of samples, respectively; SSTR3 was not expressed." (PMID 39011594, 2024). "The recurrent meningioma exhibited membranous SSTR1 staining, whereas SSTR2 showed additional nuclear staining." (PMID 39011594, 2024). "In canine meningiomas (n = 7), RNA expression of SSTR1, SSTR2 and SSTR5 was detected in all samples; SSTR3 RNA expression was detected in only 33% of samples." (PMID 39011594, 2024). "As SSTR2, the target receptor for 177Lu-DOTA-TATE-based PRRT is considered a specific marker for meningiomas; we additionally assessed SSTR2 levels in meningioma spheroids during culturing." (PMID 39061156, 2024). "SSTR2 and EMA are commonly used to histologically differentiate meningiomas from other neurooncological tumors." (PMID 38023177, 2023). "[68Ga]-DOTATATE is a positron emission tomography (PET) radiotracer that targets somatostatin receptor 2 (SSTR2), which is highly expressed in meningiomas, with greater affinity than other somatostatin receptor analogs." (PMID 35661809, 2022). "68Ga-DOTATATE PET studies were mostly utilized for assessing SSTR2 expression and eligibility for [177Lu]Lu-DOTATATE therapy in both recurrent meningiomas and pituitary carcinomas." (PMID 35740591, 2022). "This study aimed to develop and evaluate an anti-SSTR2 antibody–drug conjugate (ADC) to target and treat meningiomas." (PMID 34063284, 2021). "The meningioma specimens, consisting of four WHO grade I, three WHO grade II and three WHO grade III samples, were evaluated for SSTR2 expression." (PMID 33768405, 2021). "The xenografts were heterotopically inoculated, creating a model that remained representative for meningiomas, because these intracranial tumors are located outside the blood–brain-barrier (BBB) and are all SSTR2 positive." (PMID 33768405, 2021). "In this study we have generated a SSTR2-specific tracer, 800CW-TATE, and evaluated its potential for application in MFGS of meningiomas in xenograft mice models and clinical meningioma samples." (PMID 33768405, 2021). "High expression of SSTR2 has been shown to correlate with faster tumor growth rates on MRI in WHO grade I and II meningiomas." (PMID 34399805, 2021). "More recently, PET utilizing radiotracer ligands of SSTR2 with 68 Ga-DOTA have gained traction and are now used frequently in Europe in the diagnosis and treatment planning for meningiomas." (PMID 34399805, 2021). "Upon immunohistochemical staining, the cells were negative for S100, but positive for epithelial membrane antigen (EMA), somatostatin receptor 2 (SSTR2), and vimentin, which are considered biomarkers of meningioma." (PMID 31445511, 2019). "The first aim of this study was to identify the expression pattern of a series of preselected markers (EMA, PDGF-β, VEGF-α and SSTR-2) in meningiomas using TMA-IHC, which resulted in the analysis of a large collection of tested meningioma samples." (PMID 29858948, 2018). "DOTATOC is easier to handle than MET, but since the pituitary gland also expresses SSTR2 a high uptake of DOTATOC in the sella turcica is physiological and therefore an intrasellar invasion by meningioma cells cannot be differentiated." (PMID 29110720, 2017). "Given the low frequency of SSTR2-negative meningiomas, SSTR2 is not routinely included in standard-of-care pathologic evaluation of meningioma." (PMID 41497451, 2025). "Expression of SSTR2 has been reported also in the canine meningioma without significant differences between Grade I and Grade II, but much less in Grade III." (PMID 39969014, 2025).
meningioma (continued). "Besides podoplanin, somatostatin receptors, especially somatostatin receptor 2 (SSTR-2) and somatostatin receptor 5 (SSTR-5), are frequently expressed in meningiomas and are promising targets for malignant meningioma." (PMID 40430568, 2025). "IHC: EMA+, SSTR2+, CAM5.2−; morphology mirrored the CNS specimen, confirming metastatic meningioma." (PMID 41552249, 2025). "68Ga-DOTATOC has shown a great efficacy detecting SSTR2-positive incidental benign lesions, such as meningiomas, or metastatic lesions, not recognizable using standard imaging modalities." (PMID 39052066, 2024). "However, the distribution of SSTR2 and SSTR3 was lower in feline meningiomas than in human meningiomas." (PMID 39011594, 2024). "• RNA analysis showed SSTR1, SSTR2 and SSTR5 expressions in canine meningiomas." (PMID 39011594, 2024). "• Feline meningiomas exhibited SSTR1, SSTR4, SSTR5 and SSTR2 expressions." (PMID 39011594, 2024). "Only a single study on SSTR2 expression in canine meningiomas has been published; in contrast, no studies on the expression of any SSTR in feline meningiomas are available." (PMID 39011594, 2024). "Meningioma verification in the clinic depends primarily on HE histology and perhaps the immunohistochemical markers vimentin, epithelial membrane antigen (EMA), somatostatin receptor 2 (SSTR2), and Ki67/MIB-1." (PMID 37898750, 2023). "The histiocytes were positive for CD68, CD163, and ALK, and negative for EMA, PR, and SSTR2, which ruled out the diagnosis of meningioma." (PMID 36915094, 2023). "Second, 68 Ga-DOTA(TOC/NOC/TATE) PET-CT provides high-contrast images of meningiomas due to the abundance of somatostatin receptor 2 in meningiomas but not in brain (except the pituitary gland) and bone." (PMID 37898750, 2023). "SUV, SUVRsss, SUVRpit, and SUVRnorm did not correlate with WHO grade, consistent with prior histopathological studies, and suggesting that SSTR2 expression is independent of the differentiation status of meningioma tumor cells." (PMID 35661809, 2022). "Pre-treatment assessment of tracer uptake rates has been used to confirm patient eligibility (high somatostatin receptor-2 expression) for peptide receptor radionuclide therapy (PRRT) (i.e., neurotheranostics) for recurrent meningiomas and pituitary carcinomas." (PMID 35740591, 2022). "SSTR2 expression was strong in the meningioma bulk, but absent in adjacent dura mater which was non-tumorous confirmed by histopathology." (PMID 33768405, 2021). "It has been reported that somatostatin receptor 2 (SSTR2) is highly expressed in most meningiomas, but there is no effective targeted therapy approved to control meningiomas." (PMID 34063284, 2021). "Despite accumulating evidence that SSTR2-related/targeted treatments (e.g., somatostatin analogs and SSTR2-targeted PRRT) are promising and safe therapeutic options for unresectable or refractory meningiomas, several controversial areas remain." (PMID 33014821, 2020). "The meningioma was CK7-, ER- and AE1-/AE3-negative, while SSTR2-, PR- and CD68-positive." (PMID 29698064, 2018). "SSTR-2 was highly sensitive and specific and was expressed in all meningiomas in our large patient sample cohort, regardless of WHO grade." (PMID 29858948, 2018). "SSTR-2 expression was highly sensitive and specific in all 148 meningiomas, regardless of WHO grade." (PMID 29858948, 2018). "PET-tracers based either on amino acids as [11C]-Methionine (MET) and [2-18F]-fluoro-L-tyrosine (TYR) or the somatostatin receptor 2 (SSTR2) ligand [68Ga]-DOTA-D Phe 1-3Tyr3-Octreotide (DOTATOC) were shown to be beneficial for RT-planning, since these show very high meningioma to background ratios." (PMID 29110720, 2017). "In our study, meningiomas without psammoma bodies had a significantly higher expression of SSTR2." (PMID 34830858, 2021).
meningioma (continued). "For the development of a similar approach in meningioma surgery, various biomarkers have been suggested, including epithelial membrane antigen (EMA), platelet-derived growth factor beta (PDGF-β), vascular endothelial growth factor A (VEGF-α), and somatostatin receptor type 2 (SSTR-2)." (PMID 29858948, 2018). "Whereas SSTR2, SSTR3, and SSTR5 exhibit high affinity for octreotide, the frequent overexpression of the SSTR2A receptor may explain the high tracer uptake observed in meningioma patients during SSRS." (PMID 22623896, 2012). "Finally, a SSTR2 negative meningioma, although exceedingly rare, may contribute to potential misclassification of the lesions." (PMID 35661809, 2022). "While rare, the possibility of SSTR2-negative (and therefore, PET-negative) meningioma must be considered." (PMID 41497451, 2025). "Overexpression of SSTR2 potentially allows RLT with [177Lu]Lu-DOTATATE, although this treatment is not currently approved for meningiomas due to the lack of large-scale randomized trials." (PMID 37111596, 2023).